NFAT5 (nuclear factor of activated T cells 5)
Diseases named in the same sentence as NFAT5 in open-access papers (continued):
Sharing a sentence is not in itself a finding about the gene and the disease.
cancer (continued). "The role of NFAT5 has be extensively studied in the immune system, with little work related to cancer that has been reported." (PMID 31827081, 2019). "NFAT5, which can induce genomic instability by regulating inflammation, is highly correlated with eRNAs in 17 cancer types, ranging from 27.0% in READ to 63.4% in KIRP." (PMID 31594934, 2019). "There is little research regarding the role of Nuclear Factor of Activated T Cells 5 (NFAT5) in relation to carcinoma." (PMID 31827081, 2019). "In melanoma, NFAT5 was shown to react in the cell cycle and play a driving role in the development and carcinoma metastasis." (PMID 31827081, 2019). "The osmoregulatory transcription factor nuclear factor of activated T-cells 5 (NFAT5) has been shown to play an important role in the development of many types of human cancers." (PMID 29052520, 2017). "The other genes upregulated belonged mainly to the “cancer” and cell death functions (NFAT5, BMO2K, DLST, IL6ST, FAM76B, and MGA)." (PMID 22619672, 2012). "Further investigations are essential to clarify NFAT5 function across different cancer types and to explore how its modulation might yield therapeutic benefits." (PMID 40421201, 2025). "Moreover, NFAT5 promotes migration and/or invasion of some types of cells, including cancer cells, macrophages, and synovial fibroblasts." (PMID 38426494, 2024). "Recent reports also suggest that NFATc4 and NFAT5, which have not previously been extensively associated with cancer, showed otherwise." (PMID 39822413, 2024). "Our findings could help develop therapies that inhibit the metastasis of cancer cells by regulating TonEBP/NFAT5 expression." (PMID 38438872, 2024). "Specifically, NFAT5 promotes cancer progression via transcription of PGK1." (PMID 37208732, 2023). "In conclusion, we could show that the osmoregulatory NFAT5 directly drives Ranbp3l expression and that loss of RANBP3L leads to a cancer promoting phenotype associated with human RCC, predominantly the KIRC subtype." (PMID 34233711, 2021). "Recent studies have also suggested a repressor function of TAZ in differentiation of cancer cells and in the negative regulation of peroxisome proliferator-activated receptor-γ in mesenchymal stem cell differentiation, and NFAT5 in response to hyperosmotic stress and IL1β in inflammation." (PMID 33023162, 2020). "NFAT5 promotes the proliferation of lymphocytes and fibroblast-like synoviocytes and facilitates the migration of skeletal muscle myoblasts and cancer cells." (PMID 33373321, 2020). "Meanwhile, CADM1 and NFAT5 are critically involved in the migration and invasion of cancer cells." (PMID 33374139, 2020). "Therefore, in light of the dynamic interaction of cancer cells with microenvironments, it should be judiciously determined what the net in vivo effect of NFAT5 inhibition for cancer progression is." (PMID 30873159, 2019). "Recent studies revealed the potential relationship between NFAT5 and several cancers." (PMID 31827081, 2019). "NFAT5 plays different functions during cancer development and progression." (PMID 31756931, 2019). "Besides, clustering of α6β4 integrin in carcinomas enhances NFAT5 protein and hence NFAT5-dependent transcription, which promotes carcinoma invasion into surrounding tissues." (PMID 30873159, 2019). "All of these data indicated NFAT5 is a cancer suppressor gene." (PMID 29052520, 2017). "For instance, given that the cell lines used U937 and HeLa cells are in vitro models of cancer, possible regulation of NFAT5 by SIRT6, may translate into discovery of other novel regulatory steps leading to cancer." (PMID 27536992, 2016). "However, recent data also provide evidence that NFAT5 plays an important role in cancer progression by promoting the formation of metastasis." (PMID 26741489, 2016). "However, like the other NFAT proteins, NFAT5 also regulates cancer." (PMID 39822413, 2024).
cancer (continued). "In addition to the pathogenesis of various inflammatory diseases and cancers, NFAT5 is involved in the induction of diseases by multiple viruses, such as Coxsackievirus B3 (CVB3), hepatitis B virus (HBV), HCV, lymphocytic choriomeningitis virus (LCMV), and human immunodeficiency virus-1 (HIV-1)." (PMID 37227295, 2023). "In addition, some previous reports have shown roles for NFAT5 in cancer tissues, but the details of their functions, especially in cancer progression in the microenvironment, still remain unclear." (PMID 32901097, 2021). "Nuclear factor of activated T cells 5 (NFAT5) and cyclooxygenase 2 (COX2; PTGS2) both participate in diverse pathologies including cancer progression." (PMID 38612478, 2024). "Some TFs in the module have been demonstrated to involve in cancer procession, such as CHD1, NFAT5, and POU2F1." (PMID 34513699, 2021). "We found that seven genes (ADPRH, IL1R1, KSR1, SOCS2, JAK1, NFAT5, and SSH1) were more highly expressed in the lower-TMB subtype than in the higher-TMB subtype of more than 10 cancer types." (PMID 30634925, 2019). "To investigate whether NFAT5 performs a pro-cancer function via PGK1, we over-expressed PGK1 in AsPC-1 and BxPC-3 with knockdown of NFAT5." (PMID 31827081, 2019). "Supporting this idea, recent evidence shed light on an important role of the nuclear factor of activated T cells 5 (NFAT5), a major transcription factor that regulates osmotic stress resistance genes, in promoting tumorigenesis and metastasis of several cancer types." (PMID 26439621, 2015). "NFAT5 is more abundant in high-grade tumors and modulates the expression of key genes, including COX-2 and HIF1α, suggesting an intricate interplay that may drive cancer progression." (PMID 40421201, 2025). "Importantly, SOX17 transcriptionally down-regulated DNA repair and damage response-related genes including BRCA1, BRCA2, RAD51, KU80 DNAPK, p21, SIRT1, NFAT5 and REV3L in KYSE510 radio-resistant cells to achieve the sensitization effect to anti-cancer treatment." (PMID 30777052, 2019).
infection (16 papers, 2012 to 2025). The state of being infected such as from the introduction of a foreign agent such as serum, vaccine, antigenic substance or organism. "IMPORTANCE Accumulating studies have revealed that NFAT5 regulates disease development due to infection of numerous viruses, underlying the importance of the host factor in virus pathogenesis." (PMID 37227295, 2023). "Finally, mouse experimental models analyzing the impact of NFAT5 deficiency in different scenarios support possible roles for this factor at least in inflammatory disease, infection and osmoregulatory disorders." (PMID 30949179, 2019). "Nuclear factor of activated T-cells 5 (NFAT5), an osmo-sensitive transcription factor, can be activated by isotonic stimuli, such as infection." (PMID 38426494, 2024). "Activation of NFAT5, a well-known osmoprotective factor, can be induced by isotonic stimuli, such as infection." (PMID 38426494, 2024). "Surprisingly, KRN5 showed strong inhibitory effects on virus productive infection, which is inconsistent with the findings that depletion of NFAT5 by siRNA promotes virus production." (PMID 37227295, 2023). "The effect that the NFAT5 signaling pathway has on virus productive infection was further examined using the chemical inhibitor KRN5." (PMID 37227295, 2023). "In this study, we showed that the knockdown of NFAT5 by siRNA increased BoHV-1 productive infection and overexpression of NFAT5 via plasmid transfection decreased virus production in bovine kidney (MDBK) cells." (PMID 37227295, 2023). "BoHV-1 productive infection altered nucleus accumulation of NFAT5 isoforms and transcription of its downstream targets." (PMID 37227295, 2023). "The roles of NFAT5 played on BoHV-1 productive infection were analyzed in MDBK cells by knockdown of NFAT expression using specific siRNA." (PMID 37227295, 2023). "Ddx3x and Nfat5 have been reported to regulate the immune responses during pathogen infection in humans and mice." (PMID 33061243, 2020). "Since FL NFAT5 protein level is decreased due to cleavage of the protein by viral protease during infection, upregulating NFAT5 expression is a rational strategy to counteract CVB3 infection." (PMID 29220410, 2017). "To confirm the specificity of this cleavage, we constructed pEGFP-myc-NFAT5, a plasmid expressing NFAT5 tagged with a 6-myc peptide at its N-terminus, and transfected this plasmid into HeLa cells followed by infection with CVB3." (PMID 29220410, 2017). "While NF-κB presence in the nucleus declines in the hours post MTb infection, NFAT5 levels escalate." (PMID 22496647, 2012). "Given that the NF-κB and NFAT5 binding motifs overlap, how do NF-κB and NFAT5 function at this overlapping or shared site in the LTR to drive viral transcription in response to MTb infection?" (PMID 22496647, 2012). "Because NFAT5 expression continues to rise for at least 48 hours post-MTb infection, one possibility is that the host factors NF-κB and NFAT5 associate with the LTR at different stages after viral activation." (PMID 22496647, 2012). "HIV-1 replication was suppressed at days 6 and 9 post-infection in the NFAT5 siRNA-treated cells as compared to cells treated with control siRNA, and it was significantly inhibited by day 12 post-infection (p<0.05)." (PMID 22496647, 2012). "In summary, these studies indicated that virus productive infection at late stages of may have effects on NFAT5 signaling pathway via relocalization of NFAT5 proteins and changed accumulation of NFAT5 in distinct subcellular fractions." (PMID 37227295, 2023). "At 16 and 24 h after infection, NFAT5 protein levels were similar to mock-infected cells." (PMID 37227295, 2023). "Thus, knockdown of NFAT5 expression by siRNA increases viral productive infection, suggesting that NFAT5 is a host factor that can restrict virus productive infection." (PMID 37227295, 2023). "BoHV-1 productive infection altered the accumulation of NFAT5 proteins in mitochondria." (PMID 37227295, 2023).
infection (continued). "Here, we report that NFAT5 has capacity to restrict BoHV-1 productive infection in vitro." (PMID 37227295, 2023). "To further evaluate this hypothesis, we investigated the interplay between NFAT5 and BoHV-1 productive infection." (PMID 37227295, 2023). "To understand whether the NFAT5 signaling affects BoHV-1 productive infection in cell culture, we initially examined NFAT5 protein levels following infection of bovine kidney (MDBK) cells at later stages." (PMID 37227295, 2023). "In addition to increasing Nos2 expression, HS-induced Nfat5 expression facilitates autolysosome formation upon infection, which is critically required for HS-boosted antibacterial activity directed against E. coli." (PMID 32569301, 2020). "Given that macrophages, which are the primary target of MTb infection, are also a major reservoir of HIV-1 as infection progresses, we next investigated whether MTb is able to directly enhance NFAT5 mRNA expression in primary human MDM." (PMID 22496647, 2012). "Because NFAT5 may have distinct biological functions at distinct subcellular locations in response to diverse stimulators, confocal microscopy was performed to assess whether NFAT5 localization was influenced at 24 h after infection." (PMID 37227295, 2023). "In addition, we found that NFAT5 is a host factor limiting the virus’s productive infection." (PMID 37227295, 2023). "Interestingly, hypertonicity enhanced iNOS expression in cardiomyocytes in an NFAT5-dependent manner and peritoneal administration of high salt solution to mice at the time of infection enhanced iNOS expression in the heart and had a protective antiviral effect." (PMID 30949179, 2019). "Virus productive infection at later stages significantly increased transcription of NFAT5 but not appreciably alter measurable NFAT5 protein levels." (PMID 37227295, 2023). "Taking these data together, KRN5 significantly reduced virus productive infection partially via inhibition of viral gene expression, which does not support our findings that depletion of NFAT5 protein by siRNA leads to increased viral production." (PMID 37227295, 2023). "During infection with E. coli, macrophages did not induce Nfat5 RNA expression upon cardiac glycoside treatment." (PMID 38132136, 2023). "We found that LV-NFAT5 infection increased NFAT5 levels in HASMCs with or without PDGF stimulation, while siNFAT5 transfection reduced them." (PMID 33373321, 2020). "In addition, we have demonstrated that MTb infection or stimulation with the TLR2 ligand PAM3Cys, induces NFAT5 gene expression in human monocytes." (PMID 22496647, 2012). "Stimulation with MTb lysate significantly increased NFAT5 mRNA levels at 24 (p<0.05) and 48 (p<0.01) hours, whereas infection with viable or heat-inactivated HIV-1 isolates did not increase NFAT5 mRNA levels." (PMID 22496647, 2012). "Later, as a mechanism to combat infection and regulate pro-inflammatory cytokine, Leishmania may modulate host machinery to activate SHP-1, a phosphatase, and to inactivate NFAT5, and therefore the chromatin architecture changes entirely, which activates the IL-10 gene." (PMID 38299832, 2024). "Finally, Nfat5 belongs to the NFAT gene family, responsible for inducing an independent response to activate transcription factors involved in IFN- production in T cells in response to infection by pathogens such as T. cruzi." (PMID 34289913, 2021). "Indeed, we observed a significant increase in NFAT5 protein level at early time points (~2 h pi) in HeLa cells infected with CVB3, but to our surprise, it decreased rapidly and was undetectable 4 h after infection." (PMID 29220410, 2017). "At 24 h before infection, we replaced the growth medium with Dulbecco’s modified Eagle’s medium (DMEM) containing an additional 100 mM NaCl, a concentration reported to be high enough to induce NFAT5 expression but that is not cytotoxic, and then infected the HeLa cells with CVB3." (PMID 29220410, 2017).
kidney disease (5 papers, 2017 to 2025). "However hypertonic stress occurs rarely in organs other than the kidney, thus few studies have linked NFAT5 to non-kidney diseases despite its ubiquitous expression throughout the body." (PMID 29220410, 2017). "A high salt associated tonicity stress mediating upregulation of the transcription factor NFAT5 (nuclear factor of activated T cells, also known as tonicity-responsive enhancer-binding protein, TonEBP) resulting in inflammatory responses is well-documented in cardiac and renal diseases." (PMID 33918403, 2021). "In MCD cells exposed to 2-bromoethanamine, a nephrotoxic compound mimicking analgesic-induced nephropathy, NFAT5 fails to translocate to the nucleus under hyperosmolar stress." (PMID 40421201, 2025). "Whether NFAT5 regulation of A2M is important to non-diabetic kidney disease requires further study." (PMID 39595620, 2024).
cardiovascular disease (4 papers, 2021 to 2025). "NFAT protein family is the main substrate of CaN and includes NFAT1 (NFATc2), NFAT2 (NFATc1), NFAT3 (NFATc4), NFAT4 (NFATc3) and NFAT5, among which NFATc3 protein is highly related to the development of cardiovascular disease." (PMID 37735624, 2023). "This section summarizes the roles of NFAT5 and the respective signalling responses involved in several cardiovascular disorders." (PMID 34064510, 2021). "Since the heart is not regularly exposed to hypertonic fluids like the kidneys, cardiovascular diseases related to NFAT5 expression have not been widely studied in the past and are now an emerging field of research." (PMID 34064510, 2021). "As the heart, unlike the kidneys, is not normally exposed to hypertonic environments, studies on NFAT5-mediated cardiovascular diseases are just emerging and rapidly progressing." (PMID 34064510, 2021).
retinopathy (4 papers, 2016 to 2021). "NFAT5 deficiency decreases AR expression and alleviates the retinopathy." (PMID 33015193, 2020). "In this context, it is relevant to note that high glucose-induced hyperosmolarity seems to promote angiogenesis and retinopathy through activation of the transcription factor tonicity-responsive binding-protein (TonEBP)/nuclear factor of activated T-cells 5 (NFAT5)." (PMID 29614818, 2018).
bacterial infection (2 papers, 2024 to 2025). "The transcriptional activity of NFAT5 was assessed, and through bacterial infection experiments, the impact of NFAT5 expression on the immune response in B. belcheri was observed." (PMID 40076009, 2025). "NFAT5 is a pleiotropic stress protein with a protective role in cellular adaption to osmotic stress, bacterial infection, and genotoxin-induced DNA damage." (PMID 38612478, 2024).
inflammation (2 papers, 2019 to 2021). Aberrant reaction of the microcirculation characterized by movement of fluid and leukocytes from the blood into extravascular tissues. "A single male with de novo Nuclear Factor of Activated T Cells 5 (NFAT5) haploinsufficiency presented with autoimmune enterocolopathy, unexplained infections, and bowel inflammation." (PMID 30565237, 2019).
adenocarcinoma (1 paper, 2024). A common cancer characterized by the presence of malignant glandular cells. "Taken together, these results confirm NFAT5 responsive hypoxia induction in HEC1a, verifying NFAT5 relevance in other adenocarcinoma cell lines." (PMID 38612478, 2024).
inflammatory myopathies (1 paper, 2018). "Secondly, the NFAT5 pathway has been firmly linked to nuclear factor κB (NFκB) activity, the latter a key regulator of inflammatory diseases in general and the inflammatory myopathies in particular." (PMID 30364257, 2018). "Several observations allowed us to speculate NFAT5-inducible pathways might be involved in the inflammatory myopathies." (PMID 30364257, 2018).
NFAT5 also shares sentences with these, for which no sentence is quoted: hyperlipidemia (5 papers); intracerebral hemorrhage (4); lymphopenia (3); ovarian cancer (3); prostate carcinoma (3); type 1 diabetes (3); type 2 diabetes mellitus (3); Crohn disease (2); dry eye (2); metabolic disease (2); oral squamous cell carcinoma (2); psoriasis (2); steatosis (2); age-related macular degeneration (1); Atherosclerotic lesion (1); autoimmune enteropathy (1); autoimmune type 1 diabetes (1); Behçet’s disease (1); blood disorders (1); brain diseases (1); cardiac hypertrophy (1); cataract (1); cholangiocarcinoma (1); chronic granulomatous disease (1); colorectal adenocarcinoma (1); complication (1); diabetic encephalopathy (1); dyslipidemia (1); encephalomyelitis (1); endometrial adenocarcinoma (1).
A further 36 diseases each share a sentence with NFAT5 in 1 paper.